EGFR (epidermal growth factor receptor)
Diseases named in the same sentence as EGFR in open-access papers (continued):
Sharing a sentence is not in itself a finding about the gene and the disease.
cutaneous squamous cell carcinoma (continued). "In cutaneous squamous cell carcinoma, LPCAT1 influences the described tumorigenic processes by activating the epidermal growth factor receptor (EGFR)." (PMID 38893234, 2024). "In cutaneous squamous cell carcinoma, LPCAT1 promotes progression via the EGFR-mediated AKT/p38MAPK signaling pathways." (PMID 35399731, 2022). "The emergence of highly aggressive subtypes of human cutaneous squamous cell carcinoma (SCC) often reflects increased autocrine/paracrine TGF-β synthesis and epidermal growth factor receptor (EGFR) amplification." (PMID 20204159, 2009). "Here, we present evidence that GSPs inhibit the invasive potential or migratory behavior of head and neck cutaneous squamous cell carcinoma cells through inhibition or reversal of EMT and that GSPs do so through a process that involves the reduction in EGFR expression level." (PMID 22188922, 2011). "For patients with locally advanced (la) or metastatic (m) cutaneous squamous cell carcinoma (cSCC) who are not candidates for curative surgery/radiation or systemic anti‐PD1 therapy, anti‐EGFR in combination with chemotherapy is a rational treatment option." (PMID 40405694, 2025).
endometriosis (32 papers, 2013 to 2025). The growth of functional endometrial tissue in anatomic sites outside the uterine body. "A previous study suggested that tetrahydropalmatine, an active substance in YHS, exerts a therapeutic effect on dysmenorrhea caused by endometriosis by intervening in the EGFR/PI3K/AKT signaling pathway." (PMID 40672364, 2025). "Here we provide evidence of an SNP in the EGFR gene, rs11977660 C/T, that is associated with risk of endometriosis in women in southwest China." (PMID 31027056, 2019). "Our results are consistent with the idea that EGFR expression or activity is associated with occurrence and progression of endometriosis." (PMID 31027056, 2019). "Our results suggest that the SNP rs11977660, located in intron 1 of the EGFR gene, is significantly associated with endometriosis in women from southwest China." (PMID 31027056, 2019). "Association of 2 single-nucleotide polymorphisms in the EGFR gene with risk of endometriosis in women from southwest China." (PMID 31027056, 2019). "It was reported that the EGFR gene polymorphism is involved in the endometriosis's susceptibility." (PMID 34737779, 2021). "Studies suggest that polymorphism in the EGFR gene, located in chromosomal region 7p12, may affect susceptibility to endometriosis, but results have been inconsistent." (PMID 31027056, 2019). "Our results, together with those of another study linking the EGFR 2073∗ polymorphism to risk of endometriosis, may begin to clarify genetic risk factors behind this disease." (PMID 31027056, 2019). "Differences in EGFR levels or levels may help explain individual differences in endometriosis susceptibility." (PMID 31027056, 2019). "Our results suggest that, at least in Chinese women, the EGFR SNP rs11977660 may be a useful marker for determining genetic susceptibility to endometriosis." (PMID 31027056, 2019). "Here, we chose rs11977660 and rs2072454, which are the 2 known common tag SNPs in the EGFR gene, and examined whether 2 SNPs in the EGFR gene may be associated with risk of endometriosis in a Chinese population." (PMID 31027056, 2019). "Moreover, endometriosis was associated with amplification of EGFR gene (q = 0.047), which was again confirmed by Q-PCR and correlated with EGFR RNA expression." (PMID 25658832, 2015). "Epidermal growth factor receptor negativity further differentiates adenosarcoma from sarcomatous overgrowth and carcinomas, aligning it more closely with endometrial polyps and endometriosis." (PMID 40177444, 2025). "Among the 109 mi RNA of the signature, 29 (27%) are associated with the main signaling pathways of endometriosis: PI3K/Akt, PTEN, Wnt/β-catenin, HIF1α/NF κB, and YAP/TAZ/EGFR (Annex S3)." (PMID 35160066, 2022). "Topological analysis demonstrated that major targets of S. Stoloniferum include IL-8, EGFR, TNF, and VEGFA, which are several of the causal genes of endometriosis." (PMID 33804660, 2021). "The epidermal growth factor receptor (EGFR)-MMP7 signaling pathway has been shown to be involved in the regulation of epithelial-mesenchymal transition (EMT) during the progression of endometriosis." (PMID 34827737, 2021). "The prevalence of EGFR and KRAS mutations detected in the present study is only 9.7%, lower than the one detected in our previous study (21.3%) and in those studies on endometriosis (26%) and arteriovenous malformations of the brain (48%)." (PMID 34257550, 2021). "Signaling through EGFR is a key pathway in eSF response to E2, and constitutive activation of EGFR in eSF from women with endometriosis has been reported." (PMID 32555663, 2020). "However, further studies are necessary to elucidate the precise roles of EGF and EGFR in endometriosis and related pain." (PMID 40724945, 2025).
endometriosis (continued). "EGFR inhibitors have shown therapeutic potential in experimental endometriosis models." (PMID 41239476, 2025). "Inhibition of EGFR in eSF from women with disease restores decidualization markers, underscoring the complexity of the interplay between E2 and P4 signaling in eSF in endometrium of women with endometriosis." (PMID 32555663, 2020). "EGFR activation stimulates mitotis in the endometrium, which is composed of epithelial, stromal, inflammatory, perivascular, and blood vessel cells, so it plays a central role in endometriosis." (PMID 31027056, 2019). "Furthermore, EGFR expressed frequently in CCC patients with endometriosis than in HGSC patients (44.4% vs 8.3%, P = 0.049)." (PMID 28187748, 2017). "Based on immunohistochemistry findings, EGFR protein is expressed in endometriosis specimens." (PMID 25658832, 2015). "However, as of now, ubiquitination modification of EGFR in endometriosis remains unreported." (PMID 38735939, 2024). "In the immune-related signaling pathways, there were several pathways, including “EGFR signaling pathway”, “IL-6 signaling pathway”, “JAK/STAT signaling pathway”, “MAPK signaling pathway”, “PI3K signaling pathway”, enriched in endometriosis." (PMID 36532015, 2022). "In endometriosis, PEA technology identified seven proteins up-regulated (IL-6, IL-8, CCL 19, SCF, VEGF-D, IL-6RA, MIA9) and ten proteins down-regulated (ICOSLG, EGFR, SELE, ErbB2/HER2, IL-6RA, VEGFR-2, Flt3L, CXCL10, HE4, FR-alpha)." (PMID 36009404, 2022). "The significant decrease in EGFR, ErbB2, FR-alpha, and HE4 in the PF of endometriosis patients compared to controls should be further evaluated." (PMID 32604857, 2020). "In line with this, our finding showed that there was 44.4% CCC patients with endometriosis expressed high level of EGFR, while only 8.3% patients with endometriosis in HGSC have high expression of EGFR (P = 0.049)." (PMID 28187748, 2017). "The involvement of EGFR and SRC in endometriosis has also been noted." (PMID 41239476, 2025). "According to our review of the literature here, COMP, AGT, TGFBI and ANGP4 have not yet been associated with endometriosis, while S100A8, C163A, EGFR and TIMP1 have." (PMID 34686725, 2021). "The top 5 genes were the following: EGFR, EZH2, VEGFA, JUN, and FN1 with a degree >15; thus, they might be regulated by miR-200b-3p and play important roles in the progression of endometriosis." (PMID 32802844, 2020). "Although no significant results were observed, CCC patients with endometriosis showed a higher expression rate of EGFR compared with HGSC patients (44.4% vs 8.3%, P = 0.049)." (PMID 28187748, 2017). "Secondly, our findings indicated that amplified EGFR SCNAs were more frequently observed in patients with endometriosis than in those without it." (PMID 25658832, 2015). "In contrast, patients with endometriosis and those without differed significantly with regard to 135 SCNAs, and the locus that includes EGFR gene amplification was most prominent." (PMID 25658832, 2015). "Furthermore, expression of negative regulators of EGFR signaling, TOB1 and MIG6, has been found to be reduced in women with endometriosis." (PMID 24945252, 2014). "Moreover, based on RT-PCR analysis, EGFR RNA levels were significantly higher in samples from patients with endometriosis than from those without it (P = 0.037)." (PMID 25658832, 2015). "Moreover, amplification and RNA over-expression of EGFR gene were significantly higher in CCC tissue of patients with endometriosis than from those without it." (PMID 25658832, 2015).
endometriosis (continued). "Based on CGH data and validating Q-PCR data from individual sample and high agreement (86%) and high kappa values (70%), the prevalence of endometriosis was significantly higher in patients with an amplified EGFR locus (85%) than in those without EGFR amplification (35%) (P<0.0001)." (PMID 25658832, 2015). "However, we could not determine whether amplification of EGFR triggered the progression from endometriosis to carcinoma or whether this amplification resulted from carcinogenesis because design of this study was cross sectional." (PMID 25658832, 2015).
liver disease (32 papers, 2015 to 2026). "EGFR plays a multifaceted role in liver health and its altered expression is linked to various liver diseases." (PMID 39966897, 2025). "High levels of EGFR are expressed by hepatocytes, and deletion of EGFR leads to embryonic death shortly after birth, depending on genetic association with liver disorders." (PMID 36556437, 2022). "In the context of HCV infection, one of the best characterized signaling components associated with the development and progression of liver disease is the epidermal growth factor receptor (EGFR) pathway." (PMID 32357520, 2020). "In our previous study, caffeine and gallic acid were also found to alleviate liver disease via the EGFR extracellular domain." (PMID 40565617, 2025). "Identifying regulators of EGFR activity is crucial for understanding its impact on liver tissues and developing novel therapeutic strategies for liver diseases." (PMID 39966897, 2025). "Clinical trials support the benefits of polydatin in chronic pelvic pain, liver diseases, inflammatory bowel syndrome, and EGFR-tyrosine kinase inhibitor (TKI)-related ashes." (PMID 40431024, 2025). "The etiology of liver disease and cardiovascular disease is partially overlapping, and there is a link between EGFR studies and cardiovascular disease." (PMID 37686162, 2023). "In relation to liver disease, previous studies have revealed that genistein inhibits EGFR system and has a protective effect during the processes of acute and chronic liver disease." (PMID 37227557, 2023). "Therapeutic and protective effects of polydatin have been evaluated in different clinical trials involving disorders such as chronic pelvic pain, inflammatory bowel syndrome (IBS), liver disease, and EGFR TKI-related rashes." (PMID 36235012, 2022). "Mechanistic data in liver disease models uncovered a cross-activation of the EGFR pathway by angiotensin." (PMID 35801591, 2022). "Polydatin can be a good choice in the management of chronic pelvic pain, IBS, liver disease, and EGFR TKI-related rashes." (PMID 36235012, 2022). "Collectively, these results suggest that captopril prevents fibrotic liver disease progression toward HCC development by targeting the Ang-EGFR crosstalk in vivo." (PMID 35801591, 2022). "The activation of EGFR in liver disease affects liver regeneration via the downstream signaling pathway Ras-Raf-MEK-ERK1/2, and it controls the phosphatidylinositol-3-kinase (PI3K)-Akt mechanism." (PMID 34689832, 2021). "Targeted activation of EGFR and mTOR in BECs to convert this cell population to hepatocytes could represent a therapeutic avenue to treat these patients with advanced liver disease." (PMID 36625346, 2023). "Considering EGFR is widely distributed in the vascular endothelium, the cardiovascular system might act as a mediator between anxiety disorders and liver disease." (PMID 37686162, 2023). "EGFR may act as a bridge between liver and cardiovascular disease; thus, psychological factors affecting liver disease may be related to the cardiovascular system." (PMID 37686162, 2023). "We, therefore, investigated whether captopril treatment inhibits the EGFR pathway in the DEN rat model for progressive liver disease and HCC." (PMID 35801591, 2022). "Activation of the EGF receptor (EGFR)/MAPK pathway was also observed in the cPLS liver disease model in an etiology-independent manner, as shown by enhanced EGFR phosphorylation, upregulation of EGF/EGFR expression, and induction of experimentally defined EGF target gene signatures." (PMID 35801591, 2022). "Finally, we observed that captopril strongly suppresses the EGFR signaling pathways, a well-described driver of liver disease." (PMID 35801591, 2022). "EGFR is a key regulator in early inflammation and hepatocyte proliferation in hepatic disease." (PMID 34689832, 2021). "The EGFR signalling network has been identified as a key player in liver disease." (PMID 33138772, 2020).
liver disease (continued). "In addition, EGFR inhibitors metabolisms in liver and excretes from biliary tract, suggesting that there is safety concerns in patients with advanced liver diseases." (PMID 32322693, 2020). "Through network pharmacology studies, some scholars found that the target of Yinzhihuang granule-aided liver disease treatment may be the epidermal growth factor receptor (EGFR)." (PMID 33204286, 2020). "Moreover, expression of a number genes—potential therapeutic targets in liver diseases—including EGFR, GLUD1, GNL3, and RGS5, has been shown to be modified by dietary fats and should be further investigated in this regard." (PMID 32961898, 2020). "Thus, the role of EGFR in liver diseases appears to be more complex than what anticipated." (PMID 26729094, 2015). "It was reported that EGFR signaling axis exert a major regulatory effect during liver regeneration, liver cirrhosis and HCC, showing a pivot role of EGFR signaling in the development of liver diseases." (PMID 33746755, 2021).
chronic kidney disease (31 papers, 2012 to 2025). Impairment of the renal function secondary to chronic kidney damage persisting for three or more months. "Activation of the EGFR signaling pathway is vital for renal tubular cell survival and proliferation after injury; however, persistent activation of EGFR has been implicated in the pathogenesis of kidney fibrosis, which is a hallmark of chronic kidney disease." (PMID 40141116, 2025). "Extensive research in recent decades into the role of the EGFR pathway in the kidneys has shown that EGFR signaling is significantly associated with the advancement of chronic kidney disease (CKD)." (PMID 38732362, 2024). "It has been demonstrated that AhR is more stimulated in stage 3 chronic kidney disease patients, directly associated with higher IS levels and inversely proportional to epidermal growth factor receptor (EGFR) levels." (PMID 38592263, 2024). "Chronic kidney disease (CKD) is associated with fibrosis; EGFR is activated following renal injury, and studies have suggested its potential inhibition as a treatment for CKD." (PMID 34745017, 2021). "Experimental evidence strongly supports that aberrant EGFR signaling contributes to many forms of chronic kidney disease." (PMID 40141782, 2025). "In the past decade, many studies have investigated the role of EGFR signaling in the progression of chronic kidney disease (CKD)." (PMID 33574751, 2020). "A multicenter study, including 2454 patients showed that age > 58 years, preoperative serum creatinine > 1.03 mg / mL, and EGFR < 73 mL / min/1.73 m2 had a higher probability of developing post - nephrectomy chronic renal insufficiency." (PMID 30521174, 2019). "Furthermore, studies in preclinical models of chronic kidney disease demonstrate that pharmacological inhibition of EGFR attenuates fibrosis, highlighting its potential as a therapeutic target." (PMID 40141116, 2025). "Summary of selected studies highlighting the role of EGFR signalling in Chronic Kidney Disease." (PMID 39234105, 2024). "MK hence drived cardiac remodeling in chronic kidney disease via EGFR signaling." (PMID 36204583, 2022). "Altered expression of EGFR has been observed in interstitial fibrosis, which represents one of the most common features of chronic kidney disease (CKD)." (PMID 39966897, 2025). "Signal transducer and activator of transcription 3 (STAT3), downstream signaling of EGFR and HSP27, has been reported to be associated with AKI or chronic kidney disease (CKD)." (PMID 40230054, 2025). "Numerous studies have demonstrated that transient activation of epidermal growth factor receptor (EGFR) pathway is required for promoting kidney recovery from acute injury whereas its persistent activation is involved in the progression of various chronic kidney diseases including DKD." (PMID 33574751, 2020). "Epidermal growth factor receptor (EGFR) belongs to the family of receptor tyrosine kinases and is known to be an important regulator of multiple cellular processes in cancer-related diseases, as well as in pain processing and chronic kidney disease." (PMID 30687645, 2018). "In chronic renal failure, Viau and coworkers recently provided compelling evidence that Lcn-2 plays a key role in the progression of renal failure via EGFR-mediated proliferation using a non-inflammatory polycystic kidney disease models." (PMID 23861783, 2013). "In rodent models of chronic kidney disease (CKD), TGF-alpha has been shown to promote renal parenchymal deterioration through epidermal growth factor receptor (EGFR) activation." (PMID 40322064, 2025).